IL4 (interleukin 4)
Diseases named in the same sentence as IL4 in open-access papers (continued):
Sharing a sentence is not in itself a finding about the gene and the disease.
candidiasis (16 papers, 2011 to 2024). Infection with the organism Candida. "IL-1 inhibitors (anakinra, canakinumab, and rilonacept), IL-2 inhibitors (daclizumab, and basiliximab), and IL-4 inhibitors (dupilumab) have rarely been associated with Candida infection." (PMID 38605952, 2024). "Although a Th2 response is generally considered detrimental in systemic candidiasis, IL-4 deficiency in mice enhances susceptibility to systemic murine C. albicans infection." (PMID 21603634, 2011). "Furthermore, an association was reported between chronicdisseminated candidiasis in adult acute leukaemia and the IL-4 promoterpolymorphism." (PMID 26517657, 2015). "The inhibition of IL-4 signaling, and IL-10 knockout mice have been shown to enhance resistance to candidiasis." (PMID 39062060, 2024). "Levels of interleukin IL-4, IL-8, IL-10 were quantified after Candida infection of PNT1A cells and treatment." (PMID 36555687, 2022). "Confirming our initial day 3 PI, intracellular flow, Nos3-/- mice showed significantly higher Th9 subset (CD4+IL-9+) and Th2 subset (CD4+IL-4+) induction due to dissemination candidiasis at days 2–6 PI." (PMID 31671151, 2019). "In fact, mice lacking the IFN-γ receptor are more susceptible to systemic candidiasis than IL-4-knockout (KO) mice." (PMID 39796100, 2024). "Given the detrimental role of IL-4 and IL-10 in murine candidiasis, inhibition of cytokines of Th2-type function during infection could be beneficial." (PMID 35958550, 2022). "There are conflicting reports on the role of IL-4 during candidiasis." (PMID 22114559, 2011). "Furthermore, EVs administered to mice before inducing candidiasis influenced higher levels of TNF-α, IL-4, IL-10, IL-12p70, TGF-β and IFN-γ." (PMID 39877654, 2024). "Moreover, a recent in vivo study in murine models confirmed that lactobacilli have a moderating influence on cytokine production during Candida infection where intravaginal administration of L. crispatus and L. delbrueckii lowered IFN-γ and IL-17 while increased IL-4 expression in vaginal tissue." (PMID 37529322, 2023). "However, a requirement of IL-4 has been shown for the development of protective immunity against systemic Candida infection and a previously published study has shown that the presence of TGF-β may be required for optimal development of protective Th1 responses against systemic candidiasis." (PMID 34696267, 2021). "However, we found that gpi7 mutant vaccination could significantly increase the levels of TH2-type effector cytokines, such as IL-4 and IL-13, in the spleen and serum of mice when challenged by C. albicans SC5314, which suggests that these play a role in the immunoprotection against candidiasis." (PMID 32765468, 2020).
encephalitis (16 papers, 2012 to 2026). An acute inflammatory process affecting the brain parenchyma. "KO IL-4 mice lead to increased susceptibility to severe T. gondii encephalitis, of impaired IFN-γ production." (PMID 37122740, 2023). "A combined effect of prolonged exposure to high level of pro-inflammatory cytokines (TNF-α) combined with reduced release of anti-inflammatory cytokines IL-10 and IL-4 in encephalitis conditions may cause immunologic imbalance landed with poor prognosis." (PMID 22276993, 2012). "In experimental models, Th2 cytokines (IL-2, IL-4, IL-5, and IL-10) protected JEV-infected mice against viral encephalitis, and high CSF IL-10 levels were associated with protection against brain damage." (PMID 33776990, 2021). "Genotype and allele frequencies of IL-1β, IL-4, IL-6, IL-10, and IL-17 in anti-NMDAR encephalitis and control groups." (PMID 33362683, 2020). "Other markers (e.g., IL6, TNFA, IL2 and IL4) were also up-regulated and are increased in the CNS of patients with viral encephalitis and autoimmune epilepsy." (PMID 32225060, 2020). "For instance, βArr2 inhibited the pro-inflammatory cytokines TNF-α and IL-6 and activation of transcription factor NF-κB, increased the expression of anti-inflammatory cytokines IL-10 and IL-4 in microglia for enhancing neurological function in encephalitis mice." (PMID 34787064, 2022). "IL-10 and IL-4, are two cytokines that have been found to have strong links to encephalitis." (PMID 33362683, 2020). "In rodents, a shift from TH1 to TH2 cytokine responses was assumed based on IL-4 and TGF-β elevations during the course of experimental BoDV-1 infection which led from an acute encephalitis to a chronic persistent viral infection." (PMID 35788177, 2022). "We did not identify any significant differences in SNP genotypes of IL-1β, IL-4, IL-6, IL-10, and IL-17 between anti-NMDAR encephalitis and control groups." (PMID 33362683, 2020). "Also, given that Stat6 phosphorylation is mediated by IL-4 and that IL-4-mediated inhibition of iNOS expression on macrophages is Stat6 dependent, we investigated the potential role of Stat6 in ROCV-induced encephalitis." (PMID 27334012, 2016). "IL-4 CCL11, CCL17, CCL21), Th17 (IL-17A, GM-CSF), B cell molecules (BAFF, APRIL) and other cytokine/chemokines including IL-21, IL-1b, IL-12p40, CCL2 and IL-12p70 were detected in less than 50% of patients with encephalitis." (PMID 27575749, 2016). "However, the development of encephalitis and parasite proliferation were more related to the absence of IL-4-mediated response than a strong IFN-γ response." (PMID 25386119, 2014). "For example, in EV71 patients with encephalitis, IL-13 and IL-4 were the most increased cytokines, whereas in EV71 patients without encephalitis, IL-22 and macrophage inflammatory protein-1a (MIP-1a) were the most increased cytokines." (PMID 34079547, 2021).
Hyperglycemia (16 papers, 2010 to 2025). An increased concentration of glucose in the blood. "Whereas the induction of Arg1 and Fizz1 by IL-4 was blunted, as expected, by hyperglycemia, the effect of PRMT2-deficiency in BMDMs is similar to that of hyperglycemia in that the levels of Arg1 and Fizz1 were lower than the corresponding values for the sufficient cells." (PMID 35835907, 2022). "The highest values for IL-4 was observed in conditions imitating hypoglycemia, intermediate values in normoglycemia, and the lowest values in hyperglycemia." (PMID 38542084, 2024). "We show that cytokines, such as IFNγ and IL-4, define the direction of macrophage response, whereas hyperglycemia interferes by enhancing or annulating this cytokine effect." (PMID 35163309, 2022). "The onset of hyperglycaemia in NOD mice has reduced after regulated delivery of IL-4 to pancreatic β cells in vivo using an adenoassociated vector expressing IL-4 under the control of the mouse insulin promoter." (PMID 24629100, 2014). "We have extended these initial observations, now demonstrating that IL-4 transduced DC can prevent the onset of hyperglycemia in a significant number of prediabetic mice." (PMID 20686610, 2010). "Similarly, we have reduced onset of hyperglycemia in NOD mice after regulated delivery of IL-4 to pancreatic β cells in vivo using an adenoassociated vector (AAV) expressing IL-4 under the control of the mouse insulin promoter." (PMID 20686610, 2010). "Moreover, treatment of normoglycemic NOD mice with bone marrow derived DC, genetically modified to express interleukin 4 (IL-4), reduces the onset of hyperglycemia in a significant number of animals." (PMID 20686610, 2010). "However, the hyperglycemia, hypoxia, and oxidative stress microenvironment locks macrophages into a pro-inflammatory M1 state, impairing their repolarization to regenerative M2 phenotypes even under interleukin-4 (IL-4) stimulation." (PMID 40893353, 2025). "Apart from IFNγ- and IL-4-mediated regulation of CD163, hyperglycemia elicited an additional suppression of CD163 mRNA in M(IFNγ) compared to normoglycemia." (PMID 35163309, 2022). "The key markers of oxidative stress and inflammation such as inflammatory cytokines (IL-1β, IL-6, and TNF-α) and immunoregulatory cytokines (IL-4 and IFN-γ) were increased in kidneys along with significant hyperglycemia." (PMID 25295146, 2014). "In streptozotocin-induced T1D in wild-type mice, Schistosoma mansoni infection inhibits the breakdown of pancreatic islets and hyperglycemia through increased Arg-1 and Ym1 expression rather than through processes that rely on Treg, IL-4, IL-13, and IL-10." (PMID 40299229, 2025). "This was true for hypo-, normo-, and hyperglycemia, with a few exceptions: there was a lack of statistical significance between observed differences for IL-1α, IL-2 and IL-4 in the hypoglycemic environment and non-significant differences for IL-2 in hyperglycemia." (PMID 38542084, 2024).
liver disease (16 papers, 2008 to 2025). "Additionally, liver diseases are associated with the accumulation of hepatic natural killer (NK) cells, which produce IL-4 and IL-13." (PMID 41042784, 2025). "Furthermore, associations between IL-4 polymorphisms and the risk of liver diseases have been reported." (PMID 36386790, 2022). "Furthermore, IL-4 polymorphism has also been associated with an increased risk of liver disease and severe respiratory syncytial virus (RSV) infection." (PMID 34307393, 2021). "Especially, TNF-α mediates the early stage of fatty liver disease as well as the transition to a more advanced stage of liver disease, and stimulates the release of cytokines such as IL-4 and IL-6." (PMID 26375281, 2015). "Distinct from conventional T lymphocytes, NKT cells preferentially taking the liver as their home, play a pathogenic role in various types of liver disease, secrete cytokines like IFN-γ, IL-4, and IL-17, and regulate the balance of pro- and anti-inflammatory responses in liver diseases." (PMID 34721020, 2021). "With regards to P. vivax malaria, studies have detected IL-12, but not IL-4 in the same samples or low IL-4 levels in cases with both hepatic disorders and normal liver function, whereas levels of IL-12 were high." (PMID 21917128, 2011). "In the context of liver diseases, cytokines have been assigned fundamental properties reflecting common function, including proinflammatory cytokines (e.g. IL‐1α, IL‐1β, TNF‐α, and IL‐2), immunoregulatory cytokines (e.g. IFN-γ), and anti-inflammatory cytokines (e.g. IL-10 and IL-4)." (PMID 33841403, 2021). "The enhanced monocytic CXCR1 expression could likely result from induction by Th2-cytokines, because IL-4 was found increase with progression of liver disease (not shown) and to correlate with serum IL-8 in our cohort." (PMID 21731723, 2011). "Herein, our correlation analysis denoted that the continuously intensifying liver damage, but without an effective IL-4-dependent repair mechanism, could be responsible for the liver disease progression of fascioliasis until the final death of the infected mice at 8 wpi." (PMID 35071045, 2021).
mastocytosis (16 papers, 2011 to 2025). A clonal myeloproliferative neoplasm characterized by the proliferation and accumulation of neoplastic mast cells in one or multiple organs or organ systems. "Allergy and helminths induce strongly Th2-skewed responses associated with cytokines such as IL-4, IL-5, and IL-13, with mastocytosis, eosinophilia, and antibody class-switching to produce IgE." (PMID 27980457, 2016). "It is well-known that expulsion of T. spiralis is related to prominent mastocytosis mediated by a Th2-type response involving IL-4." (PMID 31069178, 2019). "In human fascioliasis, in the acute phase, a predominant Th2 response takes over, with production of IL-4, IL-5, as well as mastocytosis, hypereosinophilia and IgE production and the absence of IFN-gamma and IL-2." (PMID 40864127, 2025). "(iii) In the amplification-of-mastocytosis phase, repeated food antigen ingestion induces the increase of CD4+TH2 cells, which provide the IL-4 signaling that induces MC progenitors to develop into MMC9s, which expand greatly after ingested antigens cross-link with MMC9 surface IgE/FcεR complex." (PMID 27853507, 2016).
non-small cell lung carcinoma (16 papers, 2002 to 2025). A group of at least three distinct histological types of lung cancer, including non-small cell squamous cell carcinoma, adenocarcinoma, and large cell carcinoma. "A recent study described an IL-4 signaling axis in BM-derived from basophils and eosinophils that drive pro-tumorigenic myelopoiesis in non-small cell lung cancer (NSCLC) model causing immunosuppressive myelopoiesis in cancer." (PMID 41236793, 2025). "From this perspective, preoperative serum interleukin-4 levels may become a useful option to assess the risk of postoperative tumor recurrence in non-small-cell lung cancer." (PMID 33255425, 2020). "In non-small cell lung cancer, dual blockade of IL-4 and PD-1 enhances antitumor immune responses, proinflammatory cytokines production and upregulation of CD8+ T cells infiltration." (PMID 38773979, 2024). "In diseases such as human cervical cancer eosinophils induce angiogenesis through expression of IL-4, IL-5, IL-10 IL-13 and IL-8) and in human non-small-cell lung cancer (NSCLC), through of the inhibition of T and NK cell function by IDO." (PMID 35406451, 2022). "Apart from NK cells, supernatant from PD-1high ILC2s infiltrating non-small cell lung cancer (NSCLC) enhanced polarization of healthy CD14+ myeloid cells into M2-like macrophages through IL-4 and IL-13." (PMID 35565201, 2022). "In non-small cell lung cancer (NSCLC), BFD decreased the expressions of IL-10, PD-L1, and CD206 in TAMs induced in vitro by PMA and IL-4." (PMID 36311793, 2022). "Non-small cell lung cancer (NSCLC) biopsy specimens have high intratumoral concentrations of CXCR2 ligands (CXCL1, CXCL5, and CXCL8) and type 2 cytokines interleukin-4 (IL-4), IL-5, IL-10, and IL-13." (PMID 23665907, 2013).
uveitis (16 papers, 2012 to 2025). An inflammatory process affecting a part of or the entire uvea. "Traditionally, pro-inflammatory Th1/Th17 immune responses are hallmark features of uveitis, while a Th2 response characterized by high levels of IL-4, IL-5, and IL-13 is associated with UC." (PMID 37396905, 2023). "Results showed, using q-PCR, that the mRNA levels of IFN-γ, IL-17, IL-4, and IL-10 in the liver tissues of the rats in the EAU group were significantly associated with the progression of uveitis." (PMID 40718791, 2025). "Data from a clinical study suggests that the levels of IL-4 increase in serum and AqH of patients with endogenous uveitis and BD, but the levels are relatively low in BD." (PMID 33816637, 2021). "We have previously reported that Th2 and Th17 cell-related cytokines; specifically IL-4, IL-10, IL-17A, IL-22, IL-31and TNFα, are exclusively elevated in the vitreous fluid of PDR compared with that of ERM, MH, or uveitis associated with sarcoidosis." (PMID 28558009, 2017). "In this study, we investigated the effect of ocular gene therapy on the development of uveitis by subretinal injection of recombinant AAV2 vector harboring genes encoding the immunoregulatory cytokines IFN-α and IL-4." (PMID 22685550, 2012). "The specific functions of IL-4 in uveitis remain to be explored." (PMID 33816637, 2021). "Furthermore, AAU patients displayed an elevated frequency of IL-10 and IL-4 expressing T cells during uveitis inactivity." (PMID 30105034, 2018). "They found higher levels of IL-1β, IL-4, IL-17A, IL-17F, IL-21, IL-22, IL-31, IFN-γ, sCD40L, and TNF-α, with a significant difference for IL-17F, in BD-recurrent uveitis patients respect to the BD-remitted uveitis group, before drug infusion." (PMID 31134098, 2019). "Percent detectable of IL-4 and IL-22 were significantly higher in PDR group than in uveitis group, although those of IFN-γ and sCD40L were significantly higher in uveitis group compared with PDR group." (PMID 26352837, 2015). "A further understanding of the exact mechanisms by which the released IFN-α and IL-4 exactly inhibit EAU will contribute to the development of efficient and safe retinal gene therapy in uveitis." (PMID 22685550, 2012). "A mild uveitis as manifested by conjunctival hyperemia or ciliary injection was observed in AAV2.IFN-α alone treated, AAV2.IL-4 alone treated, AAV2.IFN-α and AAV2.IL-4 combined treated eyes." (PMID 22685550, 2012). "Similar to AAU patients, IAU patients displayed an elevated frequency of CD4+ IL-10+ T cells in comparison with HC, regardless of uveitis activity, and increased IL-4 expression during uveitis inactivity." (PMID 30105034, 2018). "Further studies should be performed to explore whether the abnormal DNA methylation of GATA3, IL-4 and TGF-β is also correlated with other uveitis entities." (PMID 28969068, 2017). "Similar to the result of percent detectable, the vitreous levels of IFN-γ and sCD40L were significantly higher in uveitis group than in PDR group, whereas those of IL-4, IL-17A, IL-22, IL-31, and TNFα were significantly higher in PDR group compared with uveitis group." (PMID 26352837, 2015). "Vitreous samples from 60 patients with PIOL (n = 17), OCL (n = 9), uveitis (n = 23) or retinal detachment (RD) without hemorrhage (n = 11) were analyzed for IL-2, IL-4, IL-6, IL-10, IFNγ, and TNFα concentrations by CBA." (PMID 23405064, 2013).
airway allergy (15 papers, 2009 to 2026). "Basal-cell hyperplasia, which is commonly associated with allergic respiratory disease, is correlated with the basal-cell production of alarmins such as IL-33 and TSLP, as well as with IL-4/IL-13-induced gene signaling in basal cells." (PMID 39653767, 2025). "The literature shows that the contractile reactivity of the trachea in respiratory allergic diseases is accompanied by an increase in inflammatory markers such as interleukin-4 and -5 and tumor necrosis factor-α (TNF-α)." (PMID 35712706, 2022). "The rationale of this strategy stems from the notion that JAK is a tyrosine kinase involved in the signaling of T cell receptor and of several cytokines that play a pivotal role in allergic respiratory disease, such as IL-2, IL-4 and IL-9." (PMID 34680614, 2021). "In a review article, based mainly on respiratory allergy models, the authors concluded that the PD-1/PD-L1 interaction seems to induce a Th2 response, with an increase in IL-4, whereas the PD-1/PD-L2 interaction induces a Th1 response with upregulated IFN-γ." (PMID 33968057, 2021). "The rationale of this strategy derives from the data that JAK is a tyrosine kinase involved in the signaling of T cell receptor and of several cytokines that play a role in allergic respiratory disease, such as IL-2, IL-4 and IL-9." (PMID 34680614, 2021). "We believe that the complex formations of livin/GATA3 enhances the stability of livin expression that triggers the high expression of IL-4 by activating the transcription of IL4 gene and facilitates CD4+ T cells to differentiate into Th2 cells, and causes airway allergy." (PMID 35717553, 2022). "Overproduction of IL-4 plays a critical role in the pathogenesis of airway allergy." (PMID 35717553, 2022). "The immunomodulatory effects of RosA on respiratory allergies induced by the Blomia tropicalis (Bt) mite in A/J mice showed remarkable reductions in total inflammatory cells and eosinophils, as well as decreased eosinophil peroxidase activity and IL‐4 levels in BALF." (PMID 41523289, 2026). "Livin increases the expression of IL-4 and facilitates naive CD4+ T cells to differentiate into Th2 cells, which triggers airway allergy." (PMID 35717553, 2022). "In previous studies, our group used lentivirus-mediated RNAi and co-immunoprecipitation had clarified survivin had positive regulation on the expression of IL-4 in CD4 + T cells, and confirmed that survivin plays a critical role in the pathogenesis of airway allergy." (PMID 35717553, 2022).